INSYN1 (inhibitory synaptic factor 1)
Description:
Component of the protein machinery at the inhibitory synapses, probably acting as a scaffold. Inhibitory synapses dampen neuronal activity through postsynaptic hyperpolarization. This synaptic inhibition is fundamental for the functioning of the central nervous system, shaping and orchestrating the flow of information through neuronal networks to generate a precise neural code.
Synonyms: C15orf59; MGC131524; LOC388135
Tractability: No criterion of Open Targets' tractability assessment is met for any kind of drug.
Gene: Protein-coding gene on chromosome 15 (73,735,441 to 73,753,351, reverse strand). Ensembl gene ENSG00000205363.
Subcellular location: Postsynaptic density
Subcellular location (Human Protein Atlas): Cytosol; Nucleoplasm
Gene Ontology:
Molecular function: protein binding
Biological process: inhibitory postsynaptic potential; chemical synaptic transmission, postsynaptic; postsynaptic specialization organization
Cellular component: postsynaptic density; GABA-ergic synapse; postsynaptic specialization
Genetic constraint (gnomAD): Loss-of-function variants: 8 observed, 19.84 expected, observed/expected ratio (o/e) 0.4, 90% interval 0.24 to 0.73. The upper end of that interval is the gene's LOEUF score, 0.73, which puts it in group 2 of 6, group 1 being the genes least tolerant of losing a copy. Missense variants: 322 observed, 411.33 expected, observed/expected ratio (o/e) 0.78, 90% interval 0.71 to 0.86. Synonymous variants: 168 observed, 171.79 expected, observed/expected ratio (o/e) 0.98, 90% interval 0.86 to 1.11.
Homologues: Orthologues: chimpanzee INSYN1 (99% identical), macaque INSYN1 (98% identical), pig INSYN1 (92% identical), mouse Insyn1 (89% identical), rat Insyn1 (88% identical), guinea pig INSYN1 (86% identical), dog INSYN1 (84% identical), tropical clawed frog insyn1 (52% identical), zebrafish insyn1 (48% identical). Paralogues in human: PRR16 (28% identical).
Diseases named in the same sentence as INSYN1 in open-access papers:
INSYN1 is named in the same sentence as 10 diseases in open-access papers, as found by Europe PMC text mining. Sharing a sentence is not in itself a finding about the gene and the disease. The quoted sentences say what the papers report.
Anxiety (1 paper, 2019). Intense feelings of nervousness, tension, or panic often arise in response to interpersonal stresses. "To determine whether InSyn1 might have similar physiologic functions, we performed a range of tests to determine if the loss of InSyn1 leads to increase sensitivity to seizure induction, altered locomotor activity levels, anxiety, or abnormalities in measures of cognition." (PMID 31829939, 2019). "We next analyzed locomotor activity and anxiety levels of the InSyn1 KO mice in the open field." (PMID 31829939, 2019).
epilepsy syndrome (1 paper, 2019). A syndrome that has a characteristic cluster of clinical features and/or lectroencephalographic (EEG) findings that reflect underlying epileptic activity. "First, it is possible that InSyn1 KO mice manifest different types of epilepsy syndromes with no convulsion seizure phenotype, such as absence epilepsy." (PMID 31829939, 2019).
Tourette syndrome (1 paper, 2023). A neurologic disorder caused by defective metabolism of the neurotransmitters in the brain. "INSYN1 is a novel association for a cognitive trait but it has been associated with psychiatric disorders, including ADHD, PTSD, and Tourette syndrome." (PMID 37864076, 2023).
neurological disorders (1 paper, 2019). "Our analysis of InSyn1 underscores the molecular complexity of inhibition that will be critical to further unravel to better understand GABAergic control of neural network function and how it may relate to human neurological disorders." (PMID 31829939, 2019).
INSYN1 also shares sentences with these, for which no sentence is quoted: epilepsy (2 papers); Intellectual disability (2); dyslipidemia (1); psychiatric disorder (1); tumor (1); type 2 diabetes (1).